SMARCB1 (SWI/SNF related BAF chromatin remodeling complex subunit B1)
Diseases named in the same sentence as SMARCB1 in open-access papers (continued):
Sharing a sentence is not in itself a finding about the gene and the disease.
schwannomatosis (continued). "Furthermore, our investigations indicate that germline SMARCB1 mutation carriers not presenting RTs or schwannomatosis‐associated clinical symptoms may nevertheless exhibit peripheral nerve pathology as revealed by MRN." (PMID 29779243, 2018). "In addition to this position effect, the mutational spectra differ, with SMARCB1 mutations in schwannomatosis patients being predominantly nontruncating, including missense and splice-site mutations as well as in-frame deletions, that lead to the production of stable transcripts." (PMID 27921248, 2017). "In a proportion of schwannomatosis patients without identifiable germline LZTR1 or SMARCB1 PV, somatic 22q LOH has been detected in schwannomas with or without an identifiable somatic NF2 PV." (PMID 40794298, 2025). "Whole-exome sequencing with the genomic DNA from peripheral blood leukocytes showed that patient 1 with INF2 p.Gly73Asp had no germline, schwannomatosis-related gene variants including 22q loss of heterozygosity (LOH), NF1, NF2, LZTR1, SMARCB1, and COQ6." (PMID 39857711, 2025). "There was diffuse positivity for SMARCB1/BAF47/INI1 expression, without the pattern of mosaic loss that has been reported in some schwannomatosis-associated schwannomas." (PMID 37821623, 2023). "Patients with SMARCB1- and LZTR1-associated schwannomatosis often develop multiple painful non-vestibular schwannomas in the absence of meningiomas or other tumor types." (PMID 37821623, 2023). "Whilst there exists some concern over malignant potential in SMARCB1-related schwannomatosis, this does not appear to be a feature of other types of schwannomatosis." (PMID 35361920, 2022). "It is however surprising that the mother of patient II.4 (proband I.5) does not show clinical symptoms of schwannomatosis even though she also carries the germline SMARCB1 deletion." (PMID 29779243, 2018). "So far, patients with schwannomatosis and LZTR1 germline mutations have not been reported to exhibit meningiomas, in contrast to patients with SMARCB1 germline mutations." (PMID 27921248, 2017). "However, many patients and families with schwannomatosis do not have identifiable germline variants in NF2, SMARCB1, LZTR1, CDKN2A, or DGCR8, and efforts have been underway to identify other responsible molecular drivers of schwannoma predisposition." (PMID 37821623, 2023). "Furthermore, although INI1/SMARCB1 and LZTR1 mutations show strong correlation with schwannomatosis, there is no direct evidence for their role in Hippo pathway signaling." (PMID 32960816, 2020). "Finally, one patient (Family ID 219) with a clinical diagnosis of Schwannomatosis and negative for mutations in NF2, LZTR1, and SMARCB1 is under investigation for a somatic mosaicism in NF2." (PMID 31370276, 2019). "SMARCB1, LZTR1, and NF2 clearly function as classical tumour suppressor genes, and hence, it is not unreasonable to suppose that other schwannomatosis predisposition genes might also act in an onco-suppressive manner." (PMID 27921248, 2017). "However, only 5% of sporadically occurring schwannomas in patients without NF2 or schwannomatosis exhibit mosaic SMARCB1 expression." (PMID 27921248, 2017). "Consequently, 27% of sporadic schwannomatosis patients who do not exhibit germline NF2, SMARCB1, and LZTR1 mutations, but who do display tumour-specific biallelic NF2 inactivation, could, in principle, be caused by mutations in hitherto unidentified gene(s)." (PMID 27921248, 2017). "In many studies assessing the clinical symptoms of patients with schwannomatosis (SWN), no strict distinction was made between LZTR1-related or SMARCB1-related or any other type of non-NF2-related SWN." (PMID 40794298, 2025). "In this study, we performed extended genetic screening of 75 unrelated schwannomatosis patients without identified germline PVs in NF2, LZTR1, or SMARCB1." (PMID 35723634, 2022).
meningioma (71 papers, 2001 to 2025). A generally slow growing tumor attached to the dura mater. "In some cases, germline mutations in genes are thought to be related to meningioma initiation and progression, e.g., in the SMARCB1 and SMARCE1 mutations." (PMID 40283561, 2025). "Taken together, SMARCB1 germline PVs probably represent an occasional cause of meningioma predisposition." (PMID 40794298, 2025). "Another patient (#11) presented in the same surgical time, an atypical rhabdoid and teratoid tumor (AT/RT) component, SMARCB1‐deficient, a meningioma, and a MAM." (PMID 38565263, 2024). "Small series and case reports showed mutations or chromosomal losses of NF2 or SMARCB1 in MM, as well as distinct somatic mutations in samples of different meningiomas of one individual." (PMID 36781550, 2023). "SMARCB1 R386H mutation was reported in 2.4% of meningiomas, mostly in association with NF2 mutations (73.6%)." (PMID 35049691, 2022). "Aggressive NF2-mutated meningiomas acquire chromosomal instability or co-mutation in another tumor suppressor gene, SMARCB1." (PMID 34846640, 2022). "Co-mutations in NF2-mutant meningiomas included SMARCB1 (n = 3) and PTEN (n = 1) mutations (online resource)." (PMID 35943573, 2022). "For instance, we showed in a patient with five NF2-loss meningiomas, one of the tumors acquired the pathogenic SMARCB1 mutation." (PMID 35568945, 2022). "One must also consider polymorphisms as contributors to meningioma genetic profile; for instance, we have encountered a benign variant NM_003073.3:c.897G > A of the SMARCB1 gene with a population frequency of 11.40%." (PMID 35163107, 2022). "In the previous molecular study on IVMs, SMARCB1 R377H mutation was considered prognostically unfavorable as it was found in an atypical, relapsing, meningioma." (PMID 35049691, 2022). "Noteworthy, none of the cases had gene mutations typically observed in skull base meningiomas and involving AKT1, PIK3CA and SMO, while one case had co-occurring NF2 and SMARCB1 mutations previously found in sagittal meningiomas." (PMID 35049691, 2022). "NF2:SMARCB1 co-mutated meningiomas have been shown to have a higher proliferative index, are part of the pathway to aggressiveness and higher grade in meningiomas and seem to benefit from greater EOR with regards to prevention of recurrence." (PMID 35568945, 2022). "A study including 775 samples revealed that the loss of NF2 or co-occurrence with recurrent SMARCB1 mutations frequently occurs in atypical meningiomas." (PMID 35712491, 2022). "Germline mutations in SMARCB1 have been associated with familial schwannomatosis, falcine meningiomas and rhabdoid tumor formation." (PMID 34638590, 2021). "As many as 70% of NF-2-associated meningiomas of the anterior falx have SMARCB1 co-mutation, compared to 16% co-mutation rate in tumors of other locations." (PMID 34638590, 2021). "INI1 counteracts the enzymatic function of inherited SWI/SNF-deficiency and has been linked to several benign syndromic tumors including a subset of familial schwannomatosis (linked to SMARCB1) and multiple meningiomas." (PMID 34068344, 2021). "Somatic SWI/SNF-related matrix-associated actin-dependent regulation of chromatin subfamily B member 1 protein (SMARCB1) mutations have been identified in rare spontaneous meningiomas." (PMID 31470906, 2019). "Compared to grade I tumors, atypical meningiomas are more likely to harbor SMARCB1 mutations and large deletions encompassing chromosomes 1q, 6q and 14q." (PMID 30202034, 2018). "Our case illustrates that somatic SMARCB1 mutation is another genetic risk factor for sporadic multiple meningiomas, albeit rare." (PMID 30416484, 2018). "In a distinct subgroup of CNV-low but hypermethylated NF2 mutant atypical meningiomas, we observed recurrent SMARCB1 mutations." (PMID 28195122, 2017). "A first germline mutation in the SMARCB1 gene will predispose to meningioma, but this will occur only when a somatic mutation in the NF2 gene intervenes." (PMID 26173390, 2015).
meningioma (continued). "In the setting of multiple meningiomas, although NF2-SWN is the most common tumour predisposition condition for people with ≥ 2 meningiomas before age 40, peripheral schwannomas and intracranial meningiomas can be seen in the chromosome 22 condition SMARCB1-SWN." (PMID 41160189, 2025). "Sequencing efforts have primarily focused on low-grade meningiomas, while characterization of high-grade and/or metastatic tumors remains relatively infrequent; however, integrated genomic analyses have highlighted key pathways, such as the co-mutation of SMARCB1 in atypical meningiomas." (PMID 39935847, 2024). "SMARCB1 mutations have been detected in rhabdomyoma, familial schwannomatosis, small cell hepatic fibroblastoma, skeletal extracellular myxoid chondrosarcoma, undifferentiated sarcoma, epithelial sarcoma, meningiomas and poorly differentiated chordomas." (PMID 37438850, 2023). "SMARCB1 mutation has also been shown to co-occur in NF2-mutated meningiomas." (PMID 37760490, 2023). "The highest TMB (TMB: 5.13 muts/Mb) was found in the NF2/SMARCB1-mutated meningioma (24M)." (PMID 35049691, 2022). "Another NF2-mutated meningioma featured SMARCB1 R386H and BRIP2 mutations." (PMID 35049691, 2022). "Furthermore, we found two SMARCB1 mutations that co-occurred in NF2-mutant meningiomas." (PMID 35943573, 2022). "The results suggest that the inciting event for many high-grade meningiomas is a copy number loss of chromosome 22, which in addition to containing the tumor suppressor gene NF-2 may also contain other tumor suppressor genes such as SMARCB1, CHEK2, and CLH22." (PMID 34638590, 2021). "There remains a question as to why children with certain SMARCB1 mutations have a very high risk of the highly Malignant atypical teratoid Rhabdoid tumours whereas other families appear to get only schwannomas although meningiomas also occur at a variable frequency." (PMID 23036231, 2012). "It is likely that the four-hit/three-step model of tumorigenesis also accounts for other tumours in patients with SMARCB1-related SWN including meningioma and leiomyoma." (PMID 40794298, 2025). "Meningiomas are observed as single tumours in 4–5% of patients with SMARCB1-related SWN occurring predominantly in the anterior falx cerebri." (PMID 40794298, 2025). "We confirmed known associations, such as PTCH1 with MB, SMARCB1 with ATRT, and SMARCE1 with meningioma (MNG)." (PMID 39974082, 2025). "Over 80% of sporadic meningiomas fall into one of seven molecular subgroups, including NF2, TRAF7, SMARCB1, KLF4, and mutations in Hedgehog and PI3K pathways." (PMID 40637916, 2025). "The current study showed that MAM and meningioma components harbored only a hemizygous deletion of chromosome 22q including the SMARCB1 gene, whereas a homozygous deletion was present in the AT/RT component." (PMID 38565263, 2024). "Variants in SMARCB1 and SMARCE1, components of the SWI/SNF chromatin remodeling complex, are enriched in higher-grade meningiomas, and BAP1 alterations are associated with rhabdoid morphology, though the predictive ability of these events is not established." (PMID 38730704, 2024). "These alterations can co-occur with mutations in SMARCB1, which also resides on chromosome 22 near the NF2 gene, with meningiomas typically found near the midline falx." (PMID 38730704, 2024). "Variants typical for angiomatous (brain) meningioma are PIK3CA, KIT, PTPN11, CDH1, SMAD4, and SMARCB1; the variants typical for psammomatous meningioma are APC, FGFR2, HNF1A, STK11, and JAK3." (PMID 38476782, 2024). "Prior work has shown that primary atypical meningiomas, comprised mostly of NF2 mutants with genomic instability or recurrent SMARCB1 mutations, display a hypermethylated phenotype due to increased polycomb repressive complex 2 (PRC2) activity." (PMID 36937440, 2023).
meningioma (continued). "In another study of 255 meningiomas, including 63 WHO grade 1, 173 grade 2, and 19 grade 3 meningiomas, the authors found ARID1A, SMARCA4, and SMARCB1 mutations in 17.3, 3.5, and 5.1% of samples, respectively." (PMID 37173979, 2023). "FOXM1 has also been implicated as one of three genes upregulated in primary atypical meningiomas, which have also been found to demonstrate NF2 loss, genomic instability, mutations in SMARCB1, and a hypermethylated phenotype." (PMID 36686824, 2022). "Genetic alterations involving several other subunits of the SWI/SNF complex (in particular SMARCB1 and ARID1A) are found in meningioma pathogenesis and seem to be associated with more aggressive subtypes of meningioma." (PMID 33319313, 2021). "SMARCB1 is very closely associated to NF2 on chromosome 22, and co-mutation of both genes has been seen with tumorigenesis of meningiomas." (PMID 33194703, 2020). "Mutations of two core subunits of the SWI/SNF complex, SMARCB1 and SMARCE1, have been identified in familial syndromes at risk of developing meningiomas." (PMID 33194703, 2020). "This is of particular interest since several families with multiple meningiomas and schwannomas harbor germline mutations in the SWI/SNF core complex unit SMARCB1." (PMID 31470906, 2019). "Type B (a mixture of grade I and II tumors) meningiomas were characterized by chr22q/NF2 loss and co-occurrence of SMARCB1 mutations." (PMID 31652973, 2019). "More recently, a study comparing benign versus de novo atypical (grade II) meningiomas found the latter to be significantly associated with NF2 and SMARCB1 mutations." (PMID 30202034, 2018). "RUNDC3B, SCG2, SLC1A3, EXT1 (as well as RHOBTB3, TSPAN7, CAV2, MLPH) were part of the NF2/SMARCB1 expression subclass of a recent study on genomic profiling of meningioma." (PMID 29662628, 2018). "As a result, most of the previously reported meningioma mutations (NF2, TRAF7, NOTCH2, SMARCB1, CHEK2 and AKT1) were also detected in this study." (PMID 28177878, 2017). "Three cases (case 1, 3 & 7) carried loss of chromosome 22 and deletions of three known meningioma-driver genes (NF2, CHEK2 and SMARCB1)." (PMID 28177878, 2017). "We calculated the significance of association of the driver mutations (NF2, SMARCB1, TRAF7/PI3K, TRAF7/KLF4, POLR2A, Hedgehog) with atypical meningiomas." (PMID 28195122, 2017). "Here, we show that the majority of primary (de novo) atypical meningiomas display loss of NF2, which co-occurs either with genomic instability or recurrent SMARCB1 mutations." (PMID 28195122, 2017). "In addition, certain meningiomas harbor mutations in genes such as KDM5C, KDM6A, SMARCB1, and SMARCE1, which encode proteins involved in transcriptional chromatin remodeling (SMARCB1, SMARCE1) or histone demethylation (KDM5C, KDM6A)." (PMID 40787520, 2025). "Notably, the SMARCB1 gene is located on chromosome 22q11, like the neurofibromatosis 2 (NF2) gene, which is associated with meningiomas, also a female-predominant pathology." (PMID 40052132, 2025). "Although SMARCB1 mutations have previously been shown to be co-mutated in atypical meningiomas, we did not identify any SMARCB1 mutations in our study." (PMID 39935847, 2024). "Mutations in the genes AKT1, SMARCB1, and SMO are rare in cases of atypical meningiomas, and mutations in the genes KLF4 and TRAF7 are associated with an indolent clinical behavior, thus making these meningiomas have a low risk of progression." (PMID 39202270, 2024). "CDKN2A deleted meningiomas did not harbour SMARCB1, AKT1, PIK3CA, SMO, POLR2A, or RB1 somatic mutations." (PMID 37093270, 2023). "Additionally, mutations that occur in the SMARCB1 gene, which were investigated in our patient, are reported as part of the genetic profile of non-NF2 meningioma." (PMID 35163107, 2022). "Unlike NF2-mutated meningiomas, SMARCB1/NF2 co-mutations localize anterior to the coronal suture and medially along the falx." (PMID 34846640, 2022).
meningioma (continued). "In addition to NF-2, SMARCB1 is now recognized as a driver in meningioma development with a strong predilection for the anterior falx cerebri region." (PMID 34638590, 2021). "The data suggest that SMARCB1 is a tumor suppressor gene that may be important also for the oncogenesis in a subset of meningiomas." (PMID 33692948, 2021). "Some meningiomas are caused by germline mutations in the SMARCB1 gene, but here the risk for single meningiomas without the occurrence of schwannomas is rare." (PMID 26803492, 2016). "Somatic SMARCB1 mutations not present in the germline may sometimes occur in sporadic meningiomas but these are essentially rare events." (PMID 40794298, 2025). "Importantly, germline SMARCB1 PVs do not appear to be a frequent cause of multiple meningiomas even though some families with multiple meningiomas and SMARCB1-related SWN have been reported." (PMID 40794298, 2025). "Meningiomas occur with greater frequency in patients with germline mutations of genes such as type-2 neurofibromatosis (NF2), type-1 neurofibromatosis (NF1, 19–24% of adolescent meningiomas), type-1 multiple endocrine neoplasia (MEN1), SMARCB1, LZTR1, or SMARCE1 genes." (PMID 37760490, 2023). "SMARCB1, located on chromosome 22, might induce the progression of meningiomas." (PMID 35712491, 2022). "Although we have not found disease-associated variants in NF2 and SMARCB1 genes, it is still possible that undefined variants may contribute to meningioma recurrence." (PMID 35163107, 2022). "Instead, SMARCB1 mutations located at the ends of the gene, particularly non-truncating alterations, including missense variants, are most frequently associated with non-oncologic diseases and low-grade tumors such as the ones reported in CSS, meningiomas, and schwannomas." (PMID 33692948, 2021). "However, not all mutation carriers in these families had meningiomas, indicative of the variable expression of meningiomas in patients with germline SMARCB1 mutations." (PMID 27921248, 2017). "We show that the mutational background of primary atypical meningiomas to be comprised mainly of NF2 mutants, which frequently co-occur with either chromosomal instability or recurrent p.(Arg383Gln) or p.Arg386His mutations in SMARCB1 (co-occurrence P=1.2 × 10−7, Fisher’s exact test)." (PMID 28195122, 2017). "TRAF7 (along with NF2 and PI3K) associated meningiomas are more aggressive and recur at a significantly higher rate than other molecular subgroups of meningiomas (KLF4, POLR2A, and SMARCB1)." (PMID 41372821, 2025). "The most frequent CNV in sporadic meningiomas is chromosome 22q deletion, which contains NF2 and SMARCB1, among others." (PMID 34846640, 2022). "A recent study of 469 meningiomas suggested a 22x higher recurrence rate in aggressive subgroups (NF2, PI3K, HH, TRAF7) compared to others (KLF4, POLR2A, SMARCB1)." (PMID 35213082, 2022). "Of note, other common pathological relevant genes of meningiomas, including AKT1 (n = 3; 8%), CDKN2A (n = 2; 5%), SMO (n = 0; 0%), SUFU (n = 0; 0%), POLR2A (n = 6; 16%), TRAF7 (n = 1; 3%), and SMARCB1 (n = 2; 5%), were detected as well." (PMID 34778063, 2021). "Additional common pathological relevant genes of meningiomas, including AKT1 (n = 3; 8%), CDKN2A (n = 2; 5%), SMO (n = 0; 0%), SUFU (n = 0; 0%), POLR2A (n = 6; 16%), TRAF7 (n = 1; 3%), and SMARCB1 (n = 2; 5%), were observed as well." (PMID 34778063, 2021). "Next, we focused on the most common genetic alterations reported so far in meningiomas, including the NF2, SMARCB1, as well as TRAF7, AKT1, SMO, KLF4, PIK3CA, and TERT in non-NF2 mutated meningiomas." (PMID 31470906, 2019). "Next, we focused on the most prevalent genetic alterations reported in meningiomas so far, including NF2, SMARCB1, as well as TRAF7, AKT1, SMO, KLF4, PIK3CA, and TERT in non-NF2 mutated meningiomas." (PMID 31470906, 2019).